SFXN2 (sideroflexin 2)
Description:
Mitochondrial amino-acid transporter that mediates transport of serine into mitochondria. Involved in mitochondrial iron homeostasis by regulating heme biosynthesis.
Synonyms: SLC56A2
Tractability: Antibody: UniProt predicts a signal peptide or a membrane-spanning region. PROTAC: ubiquitination databases record sites on it; its protein half-life has been measured.
Gene: Protein-coding gene on chromosome 10 (102,714,538 to 102,743,492, forward strand). Ensembl gene ENSG00000156398.
Subcellular location: Mitochondrion inner membrane; Mitochondrion outer membrane
Subcellular location (Human Protein Atlas): Mitochondria
Gene Ontology:
Molecular function: protein binding; transmembrane transporter activity; monoatomic ion transmembrane transporter activity
Biological process: mitochondrial transmembrane transport; serine import into mitochondrion; monoatomic ion transmembrane transport; monoatomic ion transport; transmembrane transport
Cellular component: mitochondrial inner membrane; mitochondrial outer membrane; mitochondrion; membrane
Genetic constraint (gnomAD): Loss-of-function variants: 33 observed, 40.06 expected, observed/expected ratio (o/e) 0.82, 90% interval 0.62 to 1.1. The upper end of that interval is the gene's LOEUF score, 1.1, which puts it in group 4 of 6, group 1 being the genes least tolerant of losing a copy. Missense variants: 346 observed, 404.65 expected, observed/expected ratio (o/e) 0.86, 90% interval 0.78 to 0.94. Synonymous variants: 136 observed, 146.3 expected, observed/expected ratio (o/e) 0.93, 90% interval 0.81 to 1.07.
Homologues: Orthologues: chimpanzee SFXN2 (99% identical), dog SFXN2 (94% identical), mouse Sfxn2 (89% identical), pig SFXN2 (89% identical), rat Sfxn2 (89% identical), rabbit SFXN2 (86% identical), guinea pig SFXN2 (85% identical), tropical clawed frog sfxn2 (73% identical), zebrafish sfxn2 (71% identical), Drosophila melanogaster Sfxn2 (57% identical), Caenorhabditis elegans sfxn-2 (46% identical). Paralogues in human: SFXN1 (55% identical), SFXN3 (55% identical), SFXN5 (40% identical), SFXN4 (22% identical).
Diseases named in the same sentence as SFXN2 in open-access papers:
SFXN2 is named in the same sentence as 33 diseases in open-access papers, as found by Europe PMC text mining. Sharing a sentence is not in itself a finding about the gene and the disease. The quoted sentences say what the papers report.
schizophrenia (4 papers, 2021 to 2022). A major psychotic disorder characterized by abnormalities in the perception or expression of reality. "SMR integrative analysis identified 2 schizophrenia risk genes (SFXN2 and TMEM180) (corrected by Bonferroni multiple comparison testing)." (PMID 33768244, 2021). "For instance, the association of schizophrenia with the USMG5 gene encoding a small subunit of the mitochondrial ATP synthase (complex V), as well as with the SFXN2 gene encoding sideroflexin-2, which is involved in iron metabolism in mitochondria, has been shown." (PMID 33552387, 2021). "Meanwhile, based on our results, AS3MT, SFXN2, and PCCB may be potential biomarkers for preventing breast and thyroid cancers in patients diagnosed with schizophrenia." (PMID 36138824, 2022).
breast carcinoma (3 papers, 2022 to 2023). "Survival analyses in the present study revealed that loss of RANBP3L, GLYATL-1, ESR1, and SFXN2 was significantly related to lower RFS in breast cancer (p-value < 0.012, 1.1 × 10−6, 1 × 10−16, and 1.3 × 10−10, respectively)." (PMID 36672708, 2023). "In conclusion, AS3MT protein expression was higher in breast cancer tissues than in normal breast tissues, and SFXN2 protein expression was higher in thyroid cancer tissues than in normal tissue." (PMID 36138824, 2022). "Using TCGA gene expression data, we found that the AS3MT and PCCB genes were differentially expressed in breast cancer, and the expressions of SFXN2 and PCCB were significantly different in ovarian cancer." (PMID 36138824, 2022). "We identified that AS3MT and SFXN2 might be employed as biomarkers in the future to help SCZ patients avoid breast cancer and thyroid cancer." (PMID 36138824, 2022).
liver cancer (2 papers, 2023). An epithelial or non-epithelial malignant neoplasm that arises from the liver. "In addition, it has been reported that SFXN2 is present in four different cancer types, namely, kidney cancer, urothelial cancer, cervical cancer, and liver cancer; only for kidney cancer is SFXN2 favourable." (PMID 37020524, 2023).
multiple myeloma (2 papers, 2022 to 2025). "Although the precise mechanism by which SFXN2 regulates apoptosis remains incomopletely defined, prior research in multiple myeloma cells demonstrated that SFXN2 overexpression markedly attenuated EBSS-induced autophagy." (PMID 40894005, 2025). "Elevated SFXN2 correlates with poor clinical outcomes in multiple myeloma and acute myeloid leukemia, potentially due to its regulations of mitochondrial iron metabolism, bioenergetics, autophagy, and redox homeostasis." (PMID 40894005, 2025). "Elevated SFXN2 was associated with poor outcomes of MM patients, and anti-myeloma effect of SFXN2 knockdown was evidenced in xenograft model." (PMID 36163342, 2022). "However, it remains elusive how SFXN2 modulates mitochondrial homeostasis and cellular iron metabolism in multiple myeloma (MM)." (PMID 36163342, 2022). "Furthermore, inhibition of SFXN2 exerted effectively anti-myeloma activity in vivo by using myeloma xenograft model." (PMID 36163342, 2022).
neuroblastoma (1 paper, 2025). Neuroblastoma (NB) is the most common solid, extracranial childhood tumor. "In SH-SY5Y neuroblastoma cells, both CCCP and MPP+ treatment caused a significant SFXN2 reduction, mirroring findings in HEK293 cells." (PMID 40894005, 2025).
oral squamous cell carcinoma (1 paper, 2019). "SFXN2 is important for the invasion of oral squamous cell carcinoma, but this gene may be responsible for the invasion of BRCA cells." (PMID 31311202, 2019).
Parkinson disease (1 paper, 2025). A progressive degenerative disorder of the central nervous system characterized by loss of dopamine producing neurons in the substantia nigra and the presence of Lewy bodies in the substantia nigra and locus coeruleus. "New evidence also suggests a connection between SFXN2 and mitochondrial dysfunction related human diseases such as Parkinson’s disease (PD)." (PMID 40894005, 2025).
renal carcinoma (1 paper, 2020). A carcinoma arising from the epithelium of the renal parenchyma or the renal pelvis. "While UNC13B and SFXN2 are present in five and four tumor entities, respectively, only for renal cancer are both UNC13B and SFXN2 favorable." (PMID 32599841, 2020).
Stroke (1 paper, 2019). Sudden impairment of blood flow to a part of the brain due to occlusion or rupture of an artery to the brain. "The mRNAs of ID3, MBTPS1, NOG, and SFXN2 have lower concentrations (are down-regulated) in the stroke samples (log FC = − 0.915, − 0.356, − 0.752, − 0.301, respectively) while BMX and SLC22A11 are up-regulated (log FC = 0.456, 0.365) in the stroke patients." (PMID 31391037, 2019). "A predictive model with 89.6% accuracy was identified using 6 network-central and differentially expressed genes (ID3, MBTPS1, NOG, SFXN2, BMX, SLC22A1), characterized by large differences in association network connectivity between stroke and control samples." (PMID 31391037, 2019). "Expression values from the genes ID3, MBTPS1, NOG, SFXN2, BMX, and SLC22A1 can jointly distinguish stroke from non-stroke samples with a high level of accuracy: 89.6% of samples are correctly classified in cross-validation sampling." (PMID 31391037, 2019). "In contrast, the connectivity of the other 5 genes is higher in the stroke vs. control networks: for MBTPS1, the control and stroke d = 1 neighborhoods have 20 vs. 49 genes, respectively, for NOG 13 vs. 65, for SFXN2 42 vs. 62, for BMX 22 vs. 61, and for SLC22A1, 15 vs. 63 neighbors." (PMID 31391037, 2019).
thyroid cancer (1 paper, 2022). "Normal thyroid tissues had a medium level of SFXN2 protein expression, whereas thyroid cancer tissues had a high protein expression level." (PMID 36138824, 2022). "We evaluated immunohistochemical staining images from the HPA to learn more about AS3MT and SFXN2 protein expression in breast and thyroid cancer." (PMID 36138824, 2022). "In breast and thyroid cancer, genes corresponding to the intersection sites (rs11191419, rs13240464, rs7432375) included SFXN2, AS3MT, IMMP2L, and PCCB." (PMID 36138824, 2022).
cancer (4 papers, 2020 to 2023). A tumor composed of atypical neoplastic, often pleomorphic cells that invade other tissues. "For example, high expression of UNC13B is favorable in five and SFXN2 in four different cancer types." (PMID 32599841, 2020). "Similar to UNC13B, studies showing any functional correlation of SFXN2 with cancer progression, developments, etc. are missing." (PMID 32599841, 2020). "Within the favorable genes, UNC13B, and SFXN2 cover nine cancer types and in the same way, SLC2A1, PLS3, SLC16A1, and SLC16A3 within the unfavorable set of genes and could serve as novel target structures." (PMID 32599841, 2020). "In addition, we analyzed MMREF CoMMpass datasets of newly RNA-seq over the course of MM, and found that SFXN2 could be inferred as a proxy of cancer progression from lower to higher aggressivity, indicating that exceptionally elevated SFXN2 might predict poor clinical outcomes of MM patients." (PMID 36163342, 2022).
tumor (4 papers, 2020 to 2025). "Dysregulation of SFXN2 can lead to altered mitochondrial metabolism, which is often associated with enhanced tumor progression and metastasis." (PMID 40149981, 2025). "Collectively, these findings not only provide insights into the metabolic reprogramming of tumor cells, but also highlight the therapeutic potential of SFXN2 in combination with iron metabolism as target for prognosis and treatment in MM patients." (PMID 36163342, 2022). "The analysis of tumor weight showed that the tumors in SFXN2-KD mice were much lower than in control mice treated with Iron Dextran." (PMID 36163342, 2022). "UNC13B is favorable in five and SFXN2 in four tumor entities, implicating that these genes might have a general prognostic value." (PMID 32599841, 2020). "Tumor growth curve displayed that the tumors in control mice grew faster than SFXN2-KD mice no matter they were treated with Iron Dextran or not, while the tumor volume of SFXN2-KD mice treated with Iron Dextran was significantly decreased compared with non-treated SFXN2-KD mice." (PMID 36163342, 2022).
neurodegenerative disease (2 papers, 2024 to 2025). A disorder of the central nervous system characterized by gradual and progressive loss of neural tissue and neurologic function. "Collectively, these findings offer new insights into the regulation of SFXN2 in mitochondrial dysfunction and highlight SFXN2’s potential implications in neurodegenerative diseases, particularly PD." (PMID 40894005, 2025). "Collectively, these findings suggest that reduced SFXN2 contributes to neuronal apoptosis resulting from mitochondrial dysfunction, underscoring its potential relevance in neurodegenerative disease pathologies." (PMID 40894005, 2025). "This work identifies SFXN2, as a Parkin substrate, that mitigates mitochondrial damage and enhances cell survival, highlighting its therapeutic potential for neurodegenerative disease like PD." (PMID 40894005, 2025). "Further research is needed to elucidate the detailed mechanisms of SFXN2’s anti-apoptotic effect and to explore whether modulating SFXN proteins could be a viable neuroprotective strategy for neurodegenerative diseases." (PMID 40894005, 2025). "While SFXN2 has not been previously linked to ALS and is not reported in DisGeNET or ALSoD, its paralog, SFXN3 gene, another member of the SFXN protein family, has been associated with neurodegenerative diseases." (PMID 38672428, 2024).
infection (1 paper, 2020). The state of being infected such as from the introduction of a foreign agent such as serum, vaccine, antigenic substance or organism. "Since a significantly higher sfxn 2 expression in A. simplex (s.s.)L3 larvae compared to L4 was previously observed, the gene expression of the sideroflexin 2 in different sites of fish infection was here investigated." (PMID 32429519, 2020).
SFXN2 also shares sentences with these, for which no sentence is quoted: acute myeloid leukemia (1 paper); adult-onset Still disease (1); autism (1); cervical cancer (1); diabetes (1); epilepsy (1); Hypertension (1); iron-deficiency (1); keratosis (1); kidney cancer (1); mental disorder (1); metabolic disorder (1); monoclonal gammopathy of undetermined significance (1); myocardial ischemia (1); Obesity (1); ovarian carcinoma (1); personality disorder (1); pulmonary disorder (1); retinitis pigmentosa (1).